GABARAPL1 (GABA type A receptor associated protein like 1)
Diseases named in the same sentence as GABARAPL1 in open-access papers (continued):
Sharing a sentence is not in itself a finding about the gene and the disease.
cancer (44 papers, 2010 to 2025). A tumor composed of atypical neoplastic, often pleomorphic cells that invade other tissues. "GABARAPL1 expression is inversely correlated with cancer metastasis and its high expression is associated with a good prognosis." (PMID 37240068, 2023). "Given the growing understanding of the association between autophagy and cancer progression and metastasis, we selected GABARAPL1 to further investigate its potential as a metastasis suppressor." (PMID 27966458, 2017). "An FRSG‐based risk score effectively predicted HCC patient prognosis, and loss of GABARAPL1 conferred ferroptosis resistance of HCC cancer stem‐like cells, while overexpressing it may recover sensitivity." (PMID 36062307, 2022). "In a further study, the WNT signaling antagonist Dapper1 was induced by autophagy-accelerated Dvl2 degradation, which is mediated by GABA(A) receptor–associated protein like 1 (GABARAPL1), a cancer repressor, and p62 is required for the interaction of Dvl2 and GABARAPL1." (PMID 31126310, 2019). "Moreover, Kaplan-Meier curves analysis showed that GABARAPL1 down-regulation in cancer tissues is associated with decreased disease-free survival in CaP patients." (PMID 27966458, 2017). "GABAA-receptor-associated protein like-1 (GABARAPL1) is involved in a variety of cancers." (PMID 29088804, 2017). "Whether GABARAPL1 expression associates with cancer remains controversial." (PMID 31803623, 2019). "By comparing genes regulated by PI3Kα/PI3Kβ inhibitions, compressive stress, and REACTOME PI3K-AKT signaling in cancer pathway lists of genes, we identified only GABARAPL1 gene as a shared gene deregulated in these three signatures." (PMID 39746759, 2025). "GABARAP family members are involved in autophagosome maturation, and compared to normal tissues, the reduced expression of GABARAPL1 has been reported in various cancer cell lines." (PMID 34983465, 2022). "During EMT, cancer cells acquire mobility properties; we thus wondered about the impact of the knockout of GABARAPL1 on invasiveness and migration." (PMID 34681055, 2021). "In cancer tissue, only the GABARAPL1 mRNA level was shown to be significantly reduced, whereas those of GABARAP and GABARAPL2 were not." (PMID 30374741, 2018). "Mechanistically, p38Tbeta; MAPK mediates cancer-provoked autophagy activation by upregulating Atg8 orthologues LC3b and Gabarapl1 as well as by activating ULK1." (PMID 31225455, 2018). "Decreased GABARAPL1 expression has been reported in various cancer tissues compared to normal tissues." (PMID 27966458, 2017). "To answer this question, we examined the effect of GABARAPL1 or GABARAPL1 G116A overexpression on cancer cell phenotypes." (PMID 28915569, 2017). "In vitro, overexpression of GABARAPL1 led to an inhibition of cancer cell phenotypes (proliferation, clonogenicity, adhesion and invasion) which confirmed previous data obtained in the laboratory." (PMID 28915569, 2017). "The GABARAP gene has been described to be highly expressed in endocrine tissues while the GABARAPL1 gene is predominantly expressed in the central nervous system but they both are underexpressed in a large variety of cancer cell lines." (PMID 26474850, 2015). "We previously reported that GABARAPL1 expression was frequently downregulated in cancer cells while a high GABARAPL1 expression is a good prognosis marker for patients with lymph node-positive breast cancer." (PMID 26474850, 2015). "Regarding GABARAPL1, a low signal of unmethylation was also measured in NT samples but not in BC samples suggesting that hemi-methylation was lost in cancer cells (p = 0.0024)." (PMID 26474850, 2015). "GABARAPL1 can facilitate autophagy by anchoring autophagy receptors to the autophagosome membrane, and its expression is increased in atrophying muscles in several conditions, including cancer cachexia." (PMID 40474277, 2025). "Three genes, WIPI2, ATG16L1, and GABARAPL1, showed comparable changes in various cancers." (PMID 34636718, 2021).
cancer (continued). "GABARAPL1 was closely related to autophagy and promoted the growth of a variety of cancers." (PMID 34790582, 2021). "In addition to its function in autophagy, GABARAPL1 has a significant influence on carcinogenesis; it is expressed at low levels in various types of cancers." (PMID 34252149, 2021). "Reduced GABARAPL1 expression was observed in various cancer cell lines." (PMID 31803623, 2019). "We propose that in cancer cachexia, increased FoxO3 occupancy at pro-atrophic genes MuRF1, MAFbx/Atrogin-1, and GABARAPL1 is promoted by AMPK-mediated FoxO3 phosphorylation, which is ultimately induced by increased systemic IL6 levels and AMPK activation in skeletal muscle." (PMID 29167426, 2017). "Growing findings indicate that GABARAPL1 is a negative regulator of cancer progression." (PMID 27966458, 2017). "GABARAPL1 expression has been described to be decreased in cancer cell lines." (PMID 26474850, 2015). "Furthermore, the expression of GABARAPL1 was notably diminished in various types of cancers." (PMID 37521346, 2023). "Interestingly, GABARAPL1 appears to be more highly expressed in the CNS as compared to other family members, however its role so far has been mainly investigated in antimicrobial responses and cancer." (PMID 37358952, 2023). "In addition, Cathepsin-L, Gabarapl1 and Bnip3, which are known gene targets of FoxO in skeletal muscle involved in protein degradation through the lysosomal/autophagy pathway, were also identified as FoxO targets during cancer." (PMID 25539728, 2014). "GABARAPL1, a member of the ATG8 protein family, plays a crucial role in autophagy and has been identified as a tumor suppressor in several cancers." (PMID 40539060, 2025). "The alteration frequencies in cancer cell lines were as follows: CDKN1A (4%), DNAJB9 (6%), GABARAPL1 (5%), RAB1A (1.6%), and VAMP7 (0.6%), with amplification being the most common type of alteration." (PMID 41040512, 2025). "Finally, GABA type A receptor–associated protein like 1 gene (GABARAPL1), coding for GABARAP structural protein of the autophagosome, was the only shared target gene between PI3Kα signature, PI3Kβ signature, compressive stress signature, and “PI3K-AKT REACTOME signaling pathway in cancer” signature." (PMID 39746759, 2025). "In the Cancer Cell Line Encyclopedia (CCLE) database, ATIC was found to be overexpressed, while CDKN1A, DNAJB9, EDEM1, and GABARAPL1 exhibited lower expression levels, aligning with the gene expression patterns observed in our model equations." (PMID 41040512, 2025). "It was found that POLE2, GABARAPL1, PIK3R1, NDC80, and TPX2 play critical roles in the response and overall survival in cancer patients under PD-L1 inhibitor treatment." (PMID 37240068, 2023). "It has been shown that strong expression of GABARAPL1 attenuates AKT activation, reduces mTOR activation, and increases cancer cell invasion." (PMID 37240068, 2023). "The current study identifies p38β MAPK as a key mediator of cancer-induced autophagy activation in skeletal muscle, through activating ULK1 as well as upregulating C/EBPβ-controlled LC3b and Gabarapl1 genes." (PMID 31225455, 2018). "Here, we show that similarly to GABARAPL1, ATG9A was up-regulated in TNBC and its inhibition decreased cancer phenotypes and abilities." (PMID 30563263, 2018). "FOXO3 overexpression correlated with expression of the Gabarapl1, ATG12, PIK3C3, LC3, and Beclin1 genes in cancer tissues." (PMID 24527027, 2014). "Moreover, we found that GABARAPL1 negatively regulated EMT through its involvement in the selective degradation of the SMAD proteins, leading to the inhibition of the migratory and invasive abilities of the cancer cells." (PMID 34681055, 2021). "The prognostic value of GABARAPL1 in cancers is still not clear." (PMID 29088804, 2017).
infection (10 papers, 2017 to 2025). The state of being infected such as from the introduction of a foreign agent such as serum, vaccine, antigenic substance or organism. "Expression levels of the E3 ubiquitin ligase MuRF1 and/or the autophagy‐related genes Gabarapl1 and p62 were greater in the quadriceps and diaphragm muscles of infected animals on day 3 post‐infection." (PMID 39871399, 2025). "Our data show that the Ca2+-AMPK pathway is required for transcriptional activation of the essential autophagy genes Gabarap, Gabarapl1, Map1lc3a, and Foxo3 in the context of myeloid-specific Gabra4 signaling during infection." (PMID 40395295, 2023). "To investigate how GABRA4 is involved in autophagy during infection and inflammation, we performed qRT-PCR amplification of Gabarap and Gabarapl1, which are regulated by GABA-induced host defense in macrophages." (PMID 40395295, 2023). "Accordingly, infection with shPARP1 decreased the autophagy and related gene expression (Gabarapl1, ATG12 and LC3) and raised the expression of p62 in the myocardium, as compared to scrambled shRNA (Scr shRNA)." (PMID 30323296, 2018). "At day 3 in the TA and SOL muscles, infection triggered increases in the mRNA expression of several autophagy-related genes, including Lc3b, Gabarapl1, Bnip3, Parkin, Lamp2a, and Foxo1." (PMID 28659735, 2017). "Results showed that infection with Ad-PARP1 resulted in up-regulation of Gabarapl1, ATG12 and LC3." (PMID 30323296, 2018). "In our study, we detected greater levels of Foxo1 mRNA in the TA than in the DIA at day 3 post-infection, suggesting that Foxo1 may contribute to the up-regulation of Lc3b, Gabarapl1, and Bnip3 that is seen in the TA in response to infection." (PMID 28659735, 2017). "In contrast, in vivo infection led to upregulation of MuRF1 in quadriceps (23‐fold, p = 0.0007) and autophagy genes in both quadriceps (5.2‐fold for Gabarapl1, p = 0.03; 7‐fold for p62, p = 0.0002) and diaphragm (2.2‐fold for Gabarapl1, p = 0.03; 2.3‐fold for p62, p = 0.057)." (PMID 39871399, 2025). "When we examined lysates from infected cells, we found that CVB infection indeed reduced levels of GABARAPL1, raising the question if CVB targets GABARAP family members to escape host immunity and promote subsequent rounds of infection." (PMID 36044516, 2022). "At 6 h post-infection (hpi), the enriched pathways included proteasome, ribosome, and regulation of autophagy, with the core genes of the most significantly enriched pathway in autophagy regulation (FDR = 0.2325) including ATG12, PIK3C3, GABARAPL1, ATG4C, and ATG4A." (PMID 37515115, 2023). "The abundance of GABARAPL1, SQSTM1, and LC3BII/I ratio increased upon Sp infection with CSE pre-exposure compared to the medium control, showing that Sp infection has no additional effects on the effects induced by CSE pre-exposure on mitophagy adaptor protein levels." (PMID 35681466, 2022).
neurodegenerative disease (4 papers, 2021 to 2025). A disorder of the central nervous system characterized by gradual and progressive loss of neural tissue and neurologic function. "For example, abnormal expression of the protein glandular epithelial cell 1 (GABARAPL1/GEC1) has been associated with neurodegenerative diseases." (PMID 34944054, 2021). "Alterations in GABARAPL1 expression can affect the efficiency of autophagy and contribute to the pathogenesis of neurodegenerative diseases." (PMID 39919076, 2025).
adenocarcinoma (1 paper, 2021). A common cancer characterized by the presence of malignant glandular cells. "We also found that the most aggressive EMT+ adenocarcinoma tumors presented higher GABARAPL1 protein levels compared to the epithelial tumors." (PMID 34681055, 2021).
neurological disorders (1 paper, 2013). "Moreover, its high expression in the brain and in particular in disease-linked areas such as the substantia nigra pars compacta might set up GABARAPL1 as a potential therapeutic target for diverse neurological disorders." (PMID 23690988, 2013).
GABARAPL1 also shares sentences with these, for which no sentence is quoted: acute myocardial infarction (1 paper); Anorexia (1); autism (1); benign prostatic hyperplasia (1); colon cancer (1); cyst (1); Dysphagia (1); esophageal cancer (1); glomerulosclerosis (1); idiopathic pulmonary fibrosis (1); ischemia (1); legionellosis (1); leishmaniasis (1); lymph node (1); melanoma (1); mesenchymal tumors (1); nematode infection (1); ovarian carcinoma (1); pancreatic cancer (1); Parkinson's (1); Polypoidal choroidal vasculopathy (1); primary immunodeficiency (1); Sepsis (1); synucleinopathy (1); type 1 diabetes mellitus (1); type 2 diabetes mellitus (1); uremia (1); vitiligo (1).